CCNB1 (cyclin B1)
Diseases named in the same sentence as CCNB1 in open-access papers (continued):
Sharing a sentence is not in itself a finding about the gene and the disease.
tumor (continued). "A particular example is the 3-way correlation that involves CCNB1 and hsa-mir-150, which is observed in the top 10 3-way correlation between miRNAs, proteins and tumor purity, but the highest 4-way correlation involves these two molecular features is only 1.914 (rank 398/631,680)." (PMID 40228208, 2025). "Moreover, the overexpression of SNRPB enhanced cell proliferation and tumor growth, which was significantly mitigated by CCNB1 knockdown, confirming that CCNB1 mediated the tumor-promoting effects of SNRPB in HCC." (PMID 40682115, 2025). "Furthermore, the study verified a significant association between CCNB1 expression and immune infiltration, immune modulators, microsatellite instability (MSI), and tumor mutational burden (TMB)." (PMID 38581717, 2024). "Our findings were significant, suggesting that hypomethylation of CCNB1 may promote tumorigenesis and tumor progression." (PMID 38581717, 2024). "Furthermore, increased doses of silymarin can decrease the levels of pCdc25c, Cdc25c, pCdc2, Cdc2, and Cyclin B1 proteins in TCC-SUP tumor cells, resulting in cell cycle arrest in the G2/M phase." (PMID 39055491, 2024). "Furthermore, some studies highlighted that SCFAs can induce apoptosis in tumor cells through the expression of p21 and Bcl-2, and the downregulation of cyclin B1, A, and D1." (PMID 38792153, 2024). "CCNB1 expression, on the other hand, exhibited a significant positive correlation with tumor stage (r = 0.301, p = 0.027), suggesting that higher CCNB1 expression was related to more advanced tumor stages." (PMID 39795587, 2024). "Based on the data presented in the correlation table, Spearman’s rho correlation analysis was conducted to assess the relationships between the expression of CDC20 and CCNB1 genes and tumor characteristics such as tumor stage (pTa, T1 andT2), grade (LG and HG), and overall survival (months)." (PMID 39795587, 2024). "Additionally, the reduced level of Cyclin B1, a downstream regulatory protein of the β-catenin signaling pathway in melittin-treated tumor cells, further supports the involvement of this pathway in modulating the EMT process." (PMID 39519238, 2024). "Furthermore, cell cycle genes such as CDK5, CCNA2, CCNB1, and CCNB2, associated with tumor relapse and metastasis, are more highly expressed in DAB2IP-low Luminal A tumors." (PMID 39418101, 2024). "Another study investigating the role of CCNB1 in BC across different tumor grades found that CCNB1 gene expression varied between tumor grade groups and could play a role in tumor aggressiveness." (PMID 39795587, 2024). "Targeting CCNB1 function inhibits the proliferation of human tumor cells." (PMID 39795587, 2024). "For instance, CDC20, a known regulator of the cell cycle, may facilitate rapid tumor cell division, while CCNB1’s involvement in the G2/M transition could enhance the proliferative capacity of tumor cells." (PMID 39596419, 2024). "This study compared the expression levels of miR-4516, Wnt 8B, FZD2, DVL3, FOSL1, CDK1, CDK2, CCNA1, and CCNB1 in primary LUAD tumor tissue with those in normal lung tissue using data from The Cancer Genome Atlas (TCGA) database to assess the consistency of our findings with the human sample." (PMID 38930863, 2024). "CCNB1 has been identified as a critical target gene for promoting tumour proliferation." (PMID 36418517, 2023). "The correlation of CCNB1 with prognosis and the tumor microenvironment was explored." (PMID 37758792, 2023). "Highly expressed cyclin B1, even in the G1 phase, binds to its partner Cdk1, which phosphorylates a number of substrates regardless of the phase of the cell cycle and contributes to aggressive proliferation in tumor tissues." (PMID 37759511, 2023). "Protein-protein interaction (PPI) analysis revealed that cyclin B1 (CCNB1), mitotic arrest deficient 2 like 1 (MAD2L1), H2A family member Z (H2AFZ) and CXCL2 may be the important protein molecules involved in CXCL3-related tumor biology." (PMID 38031087, 2023).
tumor (continued). "Out of the 55 upregulated genes, a 5 gene-signature (CDK1, EZH2, CCNB1, CCNA2, and AURKA) involved in cell regeneration was positively correlated with the status of tumor hypoxia and clustered with stemness-associated genes, as recognized by Parametric Gene Set Enrichment Analysis (PGSEA)." (PMID 37189841, 2023). "At the same time, CCNB1 may be an oncogene, and it may affect the tumor microenvironment through Th2 cells." (PMID 37758792, 2023). "Also, elevation of tumor markers (SCCAg and CCNB1) in exposed workers points to the importance of periodic biological monitoring of such workers to protect them from cancer risk." (PMID 36287252, 2023). "A correlation between CCNB1 and tumor stage was observed in this study." (PMID 37758792, 2023). "In transcriptomic cohorts, high expression of CCNB1 was associated with worse outcomes which was also obvious at the protein level independent on other prognostic factors, including LVI status, tumour size, LN stage and tumour grade." (PMID 36418517, 2023). "Moreover, workers with mutant A1AT genotype had significantly high tumor markers (SCCAg and CCNB1) levels." (PMID 36287252, 2023). "Several studies have shown that CCNB1 is a potential target for tumour intervention." (PMID 37592341, 2023). "Interestingly, we investigated the cyclin B1 (a cell cycle regulator) expression in mouse tumor tissues and found that the combination of FYLM and osimertinib downregulated the protein expression level of cyclin B1." (PMID 36744262, 2023). "Furthermore, the findings from animal models suggest that high expression of CCNB1 enhances invasive tumour growth in vivo and most likely leads to lung metastasis." (PMID 36418517, 2023). "STAT3 had been found to be over-activated and played a tumor-promoting role in a variety of human cancers because STAT3 could act as a transcription factor to promote the expression of cyclin-B1, cyclin-D1, MMP2, MMP9 and other pro-tumor proteins." (PMID 37161425, 2023). "Furthermore, treatment of the CRC cell line HT-29 with the combination of Sora and radiation enhanced the cytotoxic effects of Sora, while Sora alone induced tumor cell accumulation in G2/M phase, and decreased cyclin B1 expression." (PMID 37365571, 2023). "Previous research also indicated that increasing STIL could promote CDK1/CCNB1 activity and indirectly participate in CCNB1 dependent proliferation in tumor cells." (PMID 35155425, 2022). "Additionally, some studies also reported that patients with a high CCNB1 expression are likely to experience tumour metastasis and have a poor prognosis." (PMID 36601001, 2022). "Additionally, significant promotion of the cell cycle was found in the hot tumor subgroup, as indicated by the higher expression of the important regulatory proteins Cyclin B1 and cyclin-dependent kinase 1 (CDK1), responsible for G2/M-phase progression." (PMID 36139700, 2022). "Specifically, the inhibition of DBF4, CCNA2, CCNB1, MCM6, CDC45, CHEK1, and CDC6 may be implicated in KCNQ1-mediated tumor suppression." (PMID 35216393, 2022). "In patients with PCa, high CCNB1 expression often occurred with a high tumour grade." (PMID 36601001, 2022). "We found 9 types of tumor invasive immune cells from the expression level of CCNB1 in BC." (PMID 36040381, 2022). "We found that DEGs exhibited close associations, among which the centrally located CCNB1 and KPNA2 may have potential roles in tumor progression." (PMID 36333388, 2022). "Lzts1 codes for a tumor suppressor that may stabilize the active CDC2-cyclin B1 complex and thereby contributes to the regulation of the cell cycle and the prevention of uncontrolled cell proliferation." (PMID 35267932, 2022).
tumor (continued). "So we thought CCNB1 is one of the important miRNA-target in tumor." (PMID 36545680, 2022). "CCNB1 regulates immune cell invasion in the BC microenvironment, that it could be a therapeutic target for controlling the anti-tumor immune response." (PMID 36040381, 2022). "Circ-Ccnb1 is downregulated in breast cancer and has tumor-inhibitory properties." (PMID 34583722, 2021). "Additionally, the TOP2A, RRM2, NEK2, CDK1, and CCNB1 proteins were overexpressed in tumor liver tissues as compared to normal liver tissues according to the Human Protein Atlas database and previous studies." (PMID 34681056, 2021). "Also, inhibition of the miR-335/CCNB1 pathway promotes gemcitabine-induced autophagy and tumor growth, thus enhancing gemcitabine resistance in renal cancer." (PMID 34512152, 2021). "The mechanism underlying tumor promotion involves the mediation of the cell cycle promotion rather than mitosis, as cyclin D1, but not cyclin B1, was decreased in HCT116, SUIT-2 and OE33 cells by the downregulation of SNRPE." (PMID 34202873, 2021). "CDK1/cyclin B1 complex formation has been demonstrated to mediate mitochondrial activity during cell cycle progression and stress responses, as well as to reprogram energy metabolism in adaptive tumor resistance." (PMID 34844614, 2021). "CCNB1 gene was identified as the hub gene, which was upregulated in tumour tissues." (PMID 33632229, 2021). "CCNB1 plays a significant role in the early diagnosis, tumour stage, and poor outcomes of HBV-HCC." (PMID 34603487, 2021). "The methylation levels of CCNB1 were significantly lower in tumor samples (P = 0.005), suggesting that its expression might be regulated by DNA methylation in COAD." (PMID 33996604, 2021). "However, the effects of EXO on tumor volume, tumor weight, and the expression levels of miR-139-5p, cyclin B1, and Ki-67 were removed when silencing hsa_circ_0001610 (EXOsh-circRNA)." (PMID 34462422, 2021). "However, the results of ‘Gene’ module indicated that the gene expression of CCNB1 was positively correlated with tumor purity, B cell, CD8 + T cell, macrophage, neutrophil, but not with the immune infiltration level of CD4 + T cell." (PMID 34077304, 2021). "Consistently, Western blot assay showed that the expression of CDK1 and Cyclin B1 was restored in the c-Myc overexpression tumor sample accompanied by G9a and c-Myc protein expression level returning; meanwhile, autophagy was decreased after overexpression of c-Myc in the tumor sample." (PMID 33330479, 2020). "Furthermore, CCNB1 potentially contributed to tumor cell proliferation and migration and was positively correlated to disease recurrence and poor prognosis in BCa." (PMID 31991631, 2020). "In addition, the percentage of tumor cells positive for cyclin B1 was positively correlated with UCHL1 staining intensity in our validation cohort of USC samples." (PMID 31906456, 2020). "Meanwhile, we found that both RP11-295G20.2 and CCNB1 were downregulated, whereas miR-6884-3p expression was significantly increased in the tumor xenografts derived from HCC cells transfected with sh-RP11-295G20.2 compared with that in those transfected with sh-NC." (PMID 32687483, 2020). "Then, we performed a series of functional experiments to explore whether restoration of CCNB1 expression affected the miR-6884-3p-meditated tumor-suppressive effects on HCC cells." (PMID 32687483, 2020). "The restoration of c-Myc rescued the expression of CDK1 and Cyclin B1 in tumor samples." (PMID 33330479, 2020). "Furthermore, we demonstrated that restoration of CCNB1 expression markedly abrogated the tumor-suppressive effects of miR-6884-3p in HCC cells." (PMID 32687483, 2020).
tumor (continued). "The expression of hnRNP R may also influence metastasis and tumor aggressiveness by increasing the mRNA stability of its target, Cyclin B1 and CENPF." (PMID 32967226, 2020). "On the other hand, univariable analyzes of the separate series of tumor samples were statistically significant, which means that one tissue block per patient may be sufficient to assess CCNB1 and PTTG1 expression." (PMID 31801961, 2020). "Ten of 12 transcripts that were prognostic in Gleason score 7 tumours remained prognostic in patients with Gleason 3 + 4 = 7 tumours, and multivariable logistic regression analysis showed that combining CCNB1 or UBE2C with SRD5A2 slightly improved the predictive power of the model." (PMID 30616540, 2019). "Moreover, in vivo experiments of subcutaneous tumor formation further demonstrated that miR-144 delayed tumor formation by negative regulation of CCNB1." (PMID 30651720, 2019). "Further, they reported that miR-410-3p targets cyclin B1 and acts as a tumor suppressor miR." (PMID 31165412, 2019). "Furthermore, the protein level of hnRNPR in the tumor was positively correlated with the expression of CCNB1 and CENPF in clinical samples." (PMID 31527303, 2019). "In addition, IHC staining for cyclin B1, as a late cell cycle marker, combined with CK5 expression and tumor histology in risk-stratified patients with T1 NMIBC." (PMID 30699951, 2019). "CCNB1 showed higher expression in most tumor cells compared with normal cells." (PMID 31134129, 2019). "Recently, accumulating evidence has indicated that the expression of CCNB1 may be correlated with aggressive tumor ability and poor outcome in cancer patients, including GC, which is consistent with the findings in this study." (PMID 31527303, 2019). "Ectopic expression of circ-Ccnb1 repressed tumor growth significantly (left)." (PMID 29795334, 2018). "Ectopic delivery of circ-Ccnb1 inhibited tumor growth and extended mouse viability." (PMID 29795334, 2018). "This suggested intake of circ-Ccnb1 expression plasmids into the tumor cells." (PMID 29795334, 2018). "There was dose dependent tumor growth inhibition were seen for Cyclin-B1 siRNA treating group." (PMID 29861465, 2018). "However, Cyclin-B1 targeted siRNA loaded with cholesterol-layered MPG-8-CPP reduced more than 90% of the tumor volume in a dose-dependent manner." (PMID 29861465, 2018). "In addition to the results obtained in our in vitro studies of cyclin B1 overexpression using adenovirus-expressing cyclin B1, we found that vinblastine treatment of an allograft tumor model significantly reduced tumor progression." (PMID 30327455, 2018). "The proliferation of Brca1-mutant tumor cells decreased as the amount of cyclin B1 increased." (PMID 30327455, 2018). "Functionally, miRNA activated Ccnb1 expression and regulated tumor progression." (PMID 29212202, 2017). "Given the promoting role of cyclin B1 in tumor development, cyclin B1-targeted prevention and therapy might be beneficial." (PMID 27903976, 2017). "As expected, the tumor sample population showed higher expression levels of pro-mitotic genes such as CCNB1 and MYBL2, genes that modulate the host immune response, such as SERPINB3, and the tight-junctions proteins claudin-4 and claudin-6, which are often deregulated in cancers." (PMID 27542596, 2016). "All these indicate that Hsp90 might also be involved into the cell cycle control of tumor cells and, by regulation, the level of cyclin B1." (PMID 26786409, 2016). "To determine whether Cyclin B1 alters E-cadherin expression in vivo, we evaluated E-cadherin expression in our previous tumor xenograft models by immunohistochemical staining." (PMID 25962181, 2015). "Further function study showed suppression of Cyclin B1 could promote tumor cell migration and invasion and reduce E-cadherin expression." (PMID 25962181, 2015). "6-OAP also induced downregulation of NIPA and Skp2 and up-regulation of Cyclin B1 in tumor samples." (PMID 26474281, 2015).
tumor (continued). "Our results confirm an essential role for the cdk1/CCNB1 complex in tumor cell survival." (PMID 26029996, 2015). "These discordant findings may be explained by the dissimilar expression pattern of Cyclin B1 in different tumor types." (PMID 25962181, 2015). "Statistical evidence suggested that Cyclin B1 was related to tumor malignance." (PMID 25962181, 2015). "Flow-cytometry screens can utilize the expression of Cyclin-B1 to discriminate between the cycling tumor “diploid” cells that are transitioning through the G2/M phase of the cell cycle, from the polyploid tumor cells in that are in the G0/G1 phase of the cell cycle." (PMID 24904834, 2014). "Also, inhibition of cyclin B1/Cdk1 activity has been shown to increase apoptosis in human tumour cells 36,37." (PMID 24266894, 2014). "SUV39H1 overexpression may silence cyclin B1, leading to growth arrest and decreased tumor initiation." (PMID 23705022, 2013). "Downregulated TFDP-1, CDKN2D, and SPK2 and upregulated CDC2 and CCNB1 might affect cell cycle of tumor cells." (PMID 24455688, 2013). "Furthermore, the present study also refers to the biological behavior of tumor from the standpoint of the difference in staining pattern and overexpression of cyclin B1 in different histological grades of COSCC versus VC." (PMID 23722120, 2013). "But it remains unclear how cyclin B1 overexpression is involved in oncogenesis and tumor progression." (PMID 22682366, 2012). "To determine the cell types in which the proteins were differentially expressed, we performed immunohistochemical analyses for five molecules (ACC-pS79, CHK2, IGFBP2, cyclin B1, and caveolin 1) on samples that showed difference between normal and tumor tissues." (PMID 22348039, 2012). "Striking heterogeneity in protein expression in tumor cells was observed for cyclin B1." (PMID 22348039, 2012). "Despite the important roles of cyclin B1 and Sec62 in tumor recurrence and their predictive implications, this study should be viewed as a hypothesis-generating study." (PMID 22682366, 2012). "In addition to this, western blot analysis demonstrated increased expression of both cyclin B1 and Cdc-2 in curcumin treated cells and phosphorylation of Chk2 kinase in both MiaPaCa-2 cells in culture and the Pan02 tumor xenograft tissues." (PMID 21347286, 2011). "Moreover, cyclin B1 was accumulated in samples from 6-OAP-treated mice as compared to tumor tissues from control mice." (PMID 21755010, 2011). "L50 tumours grew more slowly, showed a strong decrease in cyclin B1, over-expressed collagen IV, and had reduced laminin 332, VEGF and CD34 levels, which, collectively, may have restricted cell division, cell adhesion and neoangiogenesis." (PMID 22107808, 2011). "Notably, this applies to a compact module of cell cycle regulators, namely survivin, cyclin B1, Cdk1, Plk1, and Bub1, whose expression increased about 2-fold in tumor versus transgenic cells according to measured fold changes." (PMID 21464922, 2011). "A correlation of serum AAbs to cyclin B1 to higher level of tumor cyclin B1 expression was found." (PMID 21113302, 2010). "One can speculate on whether the prognostic impact of cyclin B1 reflects only a high tumour proliferation rate or whether high cyclin B1 may reflect also other biological properties of the tumour." (PMID 19293801, 2009). "Besides positive nodal status and large tumour size, high cyclin B1 expression was the only independent factor predicting poor OS and MFS among chemotherapy-naive patients." (PMID 19293801, 2009). "Furthermore, control HeLa cells were progressively growing, whereas the tumor growth of HeLa cells pre-treated with cyclin B1 siRNA was strongly inhibited in nude mice, indicating that cyclin B1 is indispensable for tumor growth in vivo." (PMID 19113992, 2008). "Indeed, our previous data confirm that interfering with cyclin B1 function inhibits proliferation of human tumor cells." (PMID 19113992, 2008).